SUGP2 (SURP and G-patch domain containing 2)
Description:
May play a role in mRNA splicing.
Synonyms: KIAA0365; SFRS14; SRFS14
Tractability: PROTAC: UniProt records ubiquitination sites on it; ubiquitination databases record sites on it; its protein half-life has been measured.
Gene: Protein-coding gene on chromosome 19 (18,990,888 to 19,034,040, reverse strand). Ensembl gene ENSG00000064607.
Subcellular location: Nucleus
Subcellular location (Human Protein Atlas): Nucleoplasm; Nuclear bodies
Gene Ontology:
Molecular function: RNA binding; nucleic acid binding
Biological process: RNA processing
Cellular component: nuclear body; nucleoplasm; nucleus
Genetic constraint (gnomAD): Loss-of-function variants: 24 observed, 91.81 expected, observed/expected ratio (o/e) 0.26, 90% interval 0.19 to 0.37. The upper end of that interval is the gene's LOEUF score, 0.37, which puts it in group 1 of 6, group 1 being the genes least tolerant of losing a copy. Missense variants: 1,233 observed, 1,426.9 expected, observed/expected ratio (o/e) 0.86, 90% interval 0.82 to 0.91. Synonymous variants: 473 observed, 540.82 expected, observed/expected ratio (o/e) 0.87, 90% interval 0.81 to 0.94.
Homologues: Orthologues: chimpanzee SUGP2 (99% identical), macaque SUGP2 (98% identical), pig SUGP2 (88% identical), dog SUGP2 (85% identical), guinea pig SUGP2 (74% identical), mouse Sugp2 (74% identical), rat Sugp2 (74% identical), rabbit SUGP2 (52% identical), tropical clawed frog sugp2 (28% identical), Drosophila melanogaster CG31550 (11% identical), zebrafish sugp1 (5% identical). Paralogues in human: SUGP1 (14% identical).
Diseases named in the same sentence as SUGP2 in open-access papers:
SUGP2 is named in the same sentence as 11 diseases in open-access papers, as found by Europe PMC text mining. Sharing a sentence is not in itself a finding about the gene and the disease. The quoted sentences say what the papers report.
arthropathy (1 paper, 2021). Any disorder of the joints. "In the present study, cases with SUGP2 or DENND3 HH group showed lower involvement of skin pigmentation, arthropathy, cardiac diseases, diabetes and hypogonadism, when compared to HJV HH group; and lower prevalence of cirrhosis when compared to SLC40A1 HH group." (PMID 34583728, 2021).
iron overload (1 paper, 2021). "Of the 32 patients with primary iron overload (23 were males and 9 were females), non-HFE variants were detected in 31 (31/32, 97%), including 8 pathogenic variants in HJV, 7 pathogenic variants in SLC40A1, 8 likely pathogenic variants in SUGP2 and 5 likely pathogenic variants in DENND3 cases." (PMID 34583728, 2021).
lactic acidosis (1 paper, 2016). Metabolic acidosis characterized by the accumulation of lactate in the body. "It has been shown to bind to the intronic region of the iron-sulfur cluster assembly gene (ISCU), which is affected by the hereditary myopathy with lactic acidosis (HML) mutation; however, no previous report has described involvement of SUGP2 in tumorigenesis." (PMID 27689332, 2016).
viral infections (1 paper, 2023). "Besides the splicing regulators MBNL1 and sUGP2, cluster 7 contains members of the ELAVL family, previously shown to be prone to be hijacked during viral infections." (PMID 36814457, 2023).
cancer (2 papers, 2019 to 2023). A tumor composed of atypical neoplastic, often pleomorphic cells that invade other tissues. "PRIMPOL expression was positively correlated with the levels of C4orf27, NPIPA1 (NPIP), RP4 (RHO) and SUGP2 (SFRS14) in pan-cancer." (PMID 37391787, 2023).
tumor (1 paper, 2016).
SUGP2 also shares sentences with these, for which no sentence is quoted: cardiac diseases (1 paper); Cirrhosis (1); diabetes (1); Hepatic steatosis (1); hypogonadism (1).